DLL1 (delta like canonical Notch ligand 1)
Description:
Transmembrane ligand protein of NOTCH1, NOTCH2 and NOTCH3 receptors that binds the extracellular domain (ECD) of Notch receptor in a cis and trans fashion manner. Following transinteraction, ligand cells produce mechanical force that depends of a clathrin-mediated endocytosis, requiring ligand ubiquitination, EPN1 interaction, and actin polymerization; these events promote Notch receptor extracellular domain (NECD) transendocytosis and triggers Notch signaling through induction of cleavage, hyperphosphorylation, and nuclear accumulation of the intracellular domain of Notch receptors (NICD) (By similarity). Is required for embryonic development and maintenance of adult stem cells in many different tissues and immune systeme; the DLL1-induced Notch signaling is mediated through an intercellular communication that regulates cell lineage, cell specification, cell patterning and morphogenesis through effects on differentiation and proliferation. Plays a role in brain development at different level, namely by regulating neuronal differentiation of neural precursor cells via cell-cell interaction, most likely through the lateral inhibitory system in an endogenous level dependent-manner. During neocortex development, Dll1-Notch signaling transmission is mediated by dynamic interactions between intermediate neurogenic progenitors and radial glia; the cell-cell interactions are mediated via dynamic and transient elongation processes, likely to reactivate/maintain Notch activity in neighboring progenitors, and coordinate progenitor cell division and differentiation across radial and zonal boundaries. During cerebellar development, regulates Bergmann glial monolayer formation and its morphological maturation through a Notch signaling pathway. At the retina and spinal cord level, regulates neurogenesis by preventing the premature differentiation of neural progenitors and also by maintaining progenitors in spinal cord through Notch signaling pathway. Also controls neurogenesis of the neural tube in a progenitor domain-specific fashion along the dorsoventral axis. Maintains quiescence of neural stem cells and plays a role as a fate determinant that segregates asymmetrically to one daughter cell during neural stem cells mitosis, resulting in neuronal differentiation in Dll1-inheriting cell. Plays a role in immune systeme development, namely the development of all T-cells and marginal zone (MZ) B-cells (By similarity). Blocks the differentiation of progenitor cells into the B-cell lineage while promoting the emergence of a population of cells with the characteristics of a T-cell/NK-cell precursor. Also plays a role during muscle development. During early development, inhibits myoblasts differentiation from the medial dermomyotomal lip and later regulates progenitor cell differentiation. Directly modulates cell adhesion and basal lamina formation in satellite cells through Notch signaling. Maintains myogenic progenitors pool by suppressing differentiation through down-regulation of MYOD1 and is required for satellite cell homing and PAX7 expression. During craniofacial and trunk myogenesis suppresses differentiation of cranial mesoderm-derived and somite-derived muscle via MYOD1 regulation but in cranial mesoderm-derived progenitors, is neither required for satellite cell homing nor for PAX7 expression. Also plays a role during pancreatic cell development. During type B pancreatic cell development, may be involved in the initiation of proximodistal patterning in the early pancreatic epithelium. Stimulates multipotent pancreatic progenitor cells proliferation and pancreatic growth by maintaining HES1 expression and PTF1A protein levels. During fetal stages of development, is required to maintain arterial identity and the responsiveness of arterial endothelial cells for VEGFA through regulation of KDR activation and NRP1 expression. Controls sprouting angiogenesis and subsequent vertical branch formation through regulation on tip cell differentiation. Negatively regulates goblet cell differentiation in intestine and controls secretory fat commitment through lateral inhibition in small intestine. Plays a role during inner ear development; negatively regulates auditory hair cell differentiation. Plays a role during nephron development through Notch signaling pathway. Regulates growth, blood pressure and energy homeostasis (By similarity).
Synonyms: Delta1; DL1; Delta; NEDBAS
Tractability: Antibody: its Gene Ontology location is reachable by antibodies, with high confidence; UniProt places it where antibodies can reach, with medium confidence; UniProt predicts a signal peptide or a membrane-spanning region; the Human Protein Atlas places it where antibodies can reach. PROTAC: UniProt records ubiquitination sites on it.
Gene: Protein-coding gene on chromosome 6 (170,282,202 to 170,306,565, reverse strand). Ensembl gene ENSG00000198719.
Subcellular location: Apical cell membrane; Cell junction, adherens junction; Membrane raft
Subcellular location (Human Protein Atlas): Plasma membrane
Pathways (Reactome):
Developmental Biology: Differentiation of Keratinocytes in Interfollicular Epidermis in Mammalian Skin; Formation of paraxial mesoderm; Nephron development; Somitogenesis
Disease: Constitutive Signaling by NOTCH1 HD Domain Mutants; Constitutive Signaling by NOTCH1 HD+PEST Domain Mutants; Constitutive Signaling by NOTCH1 PEST Domain Mutants; Constitutive Signaling by NOTCH1 t(7;9)(NOTCH1:M1580_K2555) Translocation Mutant
Signal Transduction: Activated NOTCH1 Transmits Signal to the Nucleus; NOTCH2 Activation and Transmission of Signal to the Nucleus; NOTCH3 Activation and Transmission of Signal to the Nucleus
Gene Ontology:
Molecular function: Notch binding; protein binding; receptor ligand activity; Tat protein binding; calcium ion binding; scaffold protein binding
Biological process: negative regulation of interleukin-10 production; neuronal stem cell population maintenance; Notch signaling pathway; positive regulation of gene expression; astrocyte development; cell differentiation; cell fate determination; cerebellar molecular layer formation; cerebellar Purkinje cell layer structural organization; clathrin-dependent endocytosis; determination of left/right symmetry; endothelial tip cell fate specification; energy homeostasis; heart looping; hemopoiesis; lateral inhibition; marginal zone B cell differentiation; negative regulation of cell differentiation; negative regulation of cell population proliferation; negative regulation of epidermal cell differentiation; negative regulation of epithelial cell differentiation; negative regulation of glial cell apoptotic process; negative regulation of myoblast differentiation; negative regulation of neuron differentiation; negative regulation of Notch signaling pathway; and 32 more
Cellular component: adherens junction; apical plasma membrane; extracellular region; membrane raft; plasma membrane; cytoplasmic vesicle; membrane
Genetic constraint (gnomAD): Loss-of-function variants: 9 observed, 66.51 expected, observed/expected ratio (o/e) 0.14, 90% interval 0.081 to 0.24. The synonymous counts are far from expectation, so gnomAD's model fits this gene poorly and the ratio says little. Missense variants: 837 observed, 967.43 expected, observed/expected ratio (o/e) 0.87, 90% interval 0.82 to 0.92. Synonymous variants: 477 observed, 397.51 expected, observed/expected ratio (o/e) 1.2, 90% interval 1.11 to 1.29.
Gene-disease validity (ClinGen):
ClinGen rates the evidence that DLL1 causes each of these diseases.
neurodevelopmental disorder with nonspecific brain abnormalities and with or without seizures (autosomal dominant): Definitive.
Homologues: Orthologues: chimpanzee DLL1 (100% identical), macaque DLL1 (98% identical), pig DLL1 (90% identical), mouse Dll1 (89% identical), rat Dll1 (88% identical), tropical clawed frog dll1 (77% identical), guinea pig DLL1 (75% identical), zebrafish dld (70% identical), zebrafish dla (68% identical), Drosophila melanogaster Delta (41% identical), Drosophila melanogaster Ser (36% identical), Caenorhabditis elegans F55H12.3 (34% identical), and 2 more. Paralogues in human: DLL4 (48% identical), JAG2 (37% identical), JAG1 (36% identical), NOTCH4 (28% identical), DNER (23% identical).
Diseases named in the same sentence as DLL1 in open-access papers:
DLL1 is named in the same sentence as 163 diseases in open-access papers, as found by Europe PMC text mining. Sharing a sentence is not in itself a finding about the gene and the disease. The quoted sentences say what the papers report.
breast carcinoma (32 papers, 2009 to 2025). "Tumor stem cells expressing the Notch ligand Dll1 are linked to chemotherapy resistance in breast cancer." (PMID 34374886, 2021). "Consistent with prognostic clinical data, we found the tumor-promoting function of DLL1 is exclusive to ERα+ luminal breast cancer, as loss of DLL1 inhibits both tumor growth and lung metastasis of luminal breast cancer." (PMID 30442981, 2019). "In contrast, high DLL1 expression was associated with enhanced survival of TNBC/basal breast cancer patients." (PMID 30442981, 2019). "Loss of DLL1 inhibits several essential processes of breast cancer, including proliferation, maintenance of breast cancer stem cell number, and angiogenesis." (PMID 30442981, 2019). "Moreover, higher DLL1 expression is specifically associated with poor prognosis in ERα+ luminal A breast cancer patients and expression levels of most other Notch ligands did not reflect prognosis." (PMID 30442981, 2019). "Pharmacologically blocking the NF-κB pathway sensitises tumour cells to doxorubicin in Dll1+ mouse breast cancer cells by promoting cell death." (PMID 41188521, 2025). "One notable aspect of this study was the fact that DLL1 in Erα− breast cancer cells apparently seemed to have a tumor suppressive function in contrary to the oncogenic function of DLL1 in Erα+ breast tumors." (PMID 38269089, 2023). "Further investigation revealed the possible involvement of DLL1 in mediating Erα+ luminal breast cancer progression by induction of tumor cell proliferation and angiogenesis." (PMID 38269089, 2023). "The undetectable expression of DLL1 in normal breast tissues and its moderate to high expression in breast cancer." (PMID 36476410, 2022). "Dll1+ quiescent BCSCs with activated canonical NF-κB signaling pathways drive resistance to chemotherapy in breast cancer treatment." (PMID 35805056, 2022). "Treatment of breast cancer cell lines with IgG-69, a Dll1 antibody, can effectively inhibit mammosphere formation." (PMID 35805056, 2022). "JAG1 was also highly expressed in grade I of breast cancer compared to other grades, and in grade, I compared to grade II, while DLL1 expression was higher in grade II and III than grade I." (PMID 36476410, 2022). "Regarding breast cancer therapy, the Delta-like ligand 1 (DLL1) in Notch signaling becomes a target for this type of cancer." (PMID 35454775, 2022). "Both JAG1 (P-value = 0.0002) and DLL1 (P-value = 0.009) showed higher expression in stage I than stage II of breast cancer." (PMID 36476410, 2022). "It has been recently reported that NF‐κB activation is a downstream target of Dll1, which collectively contributes to a chemoresistant phenotype of breast cancer CSCs." (PMID 36226253, 2022). "Increased DLL1 protein expression following estrogen treatment was also found previously in breast cancer cells." (PMID 35216398, 2022). "Recent studies have shown that Notch ligand DLL1 is highly expressed in ER + luminal breast cancer and elevated levels of DLL1 mediate tumorigenesis and metastasis." (PMID 36476410, 2022). "The most widely studied and comparatively mature is breast cancer, DLL1 overexpression leads to poor prognosis through cell proliferation, maintenance of tumor stem cells and angiogenesis." (PMID 36071128, 2022). "The expression of Dll1, a Notch ligand, promotes the tumor‐initiating abilities of breast cancer cells." (PMID 36226253, 2022). "Together, our studies identify Dll1+ cells as potential TICs with reduced proliferative potential in breast cancer." (PMID 33462238, 2021). "To explore the clinical correlation of our mouse data, we examined our Dll1+ mouse signature with METABRIC, a patient database to analyze correlation of DLL1 to NF-kB in luminal A and B breast cancer patients." (PMID 33462238, 2021). "To better understand the molecular signatures between Dll1+ and Dll1− tumor cells in breast cancer, we performed RNA-seq analysis using Dll1+ and Dll1− tumor cells from both PyMT-Dll1mCh and PyMT-Dll1GFP tumors." (PMID 33462238, 2021).
breast carcinoma (continued). "DLL1 in tumor stem cells activated Nf-kB survival pathway, which drives chemoresistance in breast cancer." (PMID 33968932, 2021). "In the ER+ luminal breast cancer, estrogen stabilizes the DLL1-induced Notch signaling activation and controls the function of CSCs." (PMID 34098945, 2021). "Using conditional knockout and reporter mouse models, we demonstrate that tumor cells expressing the Notch ligand Dll1 is important for tumor growth and metastasis and bear similarities to tumor-initiating cancer cells (TICs) in breast cancer." (PMID 33462238, 2021). "The Notch-signaling ligand DLL1 has emerged as an important player and promising therapeutic target in breast cancer (BC)." (PMID 34439228, 2021). "To dissect the role of Dll1 in autochthonous mammary tumors, we crossed Dll1 conditional-knockout (Dll1cKO) mice in which K14-Cre recombinase efficiently knocks out Dll1 in mammary epithelial cells to MMTV-PyMT to generate PyMT-Dll1cKO animals." (PMID 33462238, 2021). "In experimental models, the tumor-promoting function of DLL1 is exclusive to ER+ luminal breast cancers; in these tumors, estrogen signaling stabilizes the DLL1 protein, thus preventing its proteosomal degradation." (PMID 32210163, 2020). "DLL1 is a Notch ligand known to play a major role in cancers like breast cancer and squamous neoplasias, and it is thought to be a promising therapeutic target." (PMID 32393311, 2020). "To understand the functional role of DLL1 in growth and metastasis of human breast cancer (luminal and TNBC), we used the ERα+ luminal cell lines MCF7 and T47D, and ER− basal/TNBC cell line, HCC1806." (PMID 30442981, 2019). "It is possible that DLL1 has opposing functions in breast cancer subtypes due to its interaction with distinct cell types within the different tumor microenvironments of different subtypes, which needs further evaluation." (PMID 30442981, 2019). "Taken together, our data strongly indicate a unique function of Dll1 in promoting multiple steps of cancer growth, progression, and lung metastasis in luminal breast cancer." (PMID 30442981, 2019). "Using primary patient breast tumors, we show here for the first time that DLL1 protein expression is highly upregulated in ERα+ luminal breast cancer compared to either normal breast tissue or TNBC/basal breast cancer." (PMID 30442981, 2019). "The specificity of the anti-DLL1 antibody was validated by western blot of human breast cancer cell lines, which show a single band at the expected size of ~70 kDa." (PMID 30442981, 2019). "Using a Dll1 antibody, we now show that DLL1 protein is specifically overexpressed in ERα+ luminal breast cancer patient samples when compared to normal tissue or TNBC tumors." (PMID 30442981, 2019). "Intriguingly, DLL1 expression levels in ERα− subtypes of breast cancer, including TNBC/basal and HER2+, do not correlate with prognosis, highlighting a potential subtype-specific function for DLL1 in ERα+ breast cancer." (PMID 30442981, 2019). "In our studies we show that DLL1, a Notch signaling ligand, is significantly overexpressed in ERα+ luminal breast cancer." (PMID 30442981, 2019). "Together, our data demonstrate a novel tumor-promoting function for the Notch ligand, DLL1 in ERα+ luminal breast cancers, thereby providing initial proof-of-principle for subtype-specific therapies for luminal ERα+ breast cancer patients." (PMID 30442981, 2019). "The clinical correlation data using published datasets were further confirmed by western blot analysis of human breast cancer cells that showed that DLL1 expression is higher in three luminal breast cancer cells (MCF7, T47D and ZR-75-1)." (PMID 30442981, 2019). "Corroborating our clinical data, our functional data using mouse and human breast cancer cell lines strongly support a protumorigenic role for Dll1 in ERα+ luminal breast cancer." (PMID 30442981, 2019).